EPO (erythropoietin)
Diseases named in the same sentence as EPO in open-access papers (continued):
Sharing a sentence is not in itself a finding about the gene and the disease.
COVID-19 (continued). "For the remaining genes, the expression of both dACE2 and EPO was induced in the nasopharyngeal swabs of COVID-19 patients, failing, however, to distinguish patients with mild from the ones with severe symptoms." (PMID 36611805, 2022). "The EPO expression remained elevated in the nasopharyngeal swabs of hospitalized COVID-19 patients, yet it was severely downregulated in the whole blood samples of the respective group, compared to the healthy subjects." (PMID 36611805, 2022). "In the whole blood samples of hospitalized COVID-19 patients, dACE2 and EPO mRNA levels were diminished, compared to healthy subjects." (PMID 36611805, 2022). "The underlying beneficial effects likely go beyond erythropoiesis and include counteraction of the complex pathophysiology of COVID-19 as delineated in the present paper and previous reviews on EPO in COVID-19." (PMID 34565332, 2021). "Overall these results are in line with the proposed use of human recombinant EPO in severe COVID-19 cases as beneficial for the alleviation of respiratory inflammation." (PMID 34185793, 2021). "Along these lines of thought, people living at high-altitude have elevated levels of serum EPO and are therefore believed to be better protected from a severe course of COVID-19." (PMID 34565332, 2021). "As supporting hints, embedded in this review, we present 4 male patients with severe COVID-19 and unfavorable prognosis, including predicted high lethality, who all profoundly improved upon treatment which included erythropoietin analogues." (PMID 34565332, 2021). "Here we present four cases of severe COVID-19 and unfavorable prognosis, that received EPO analogues." (PMID 34565332, 2021). "In serum, lower levels of EPO have been detected in COVID-19 critical and deceased patient groups than in healthy ones." (PMID 34185793, 2021). "The use of recombinant erythropoietin was shown to have unexplained rapid relief and viral load regression in an 80-year-old male COVID-19 patient with severe anemia." (PMID 38624521, 2020). "We present in brief chapters the major problems of severely affected COVID-19 patients and delineate the potential of EPO to relieve them." (PMID 32546125, 2020). "We propose that EPO will act on all three major levels of respiratory function in severely affected COVID-19 patients." (PMID 32546125, 2020). "Both immunomodulation and anti-inflammation mediated by EPO promise another set of beneficial effects in severe COVID-19." (PMID 32546125, 2020). "In this context, EPO’s pleiotropic benefits may alleviate COVID-19-related complications by supporting respiration, modulating neuroinflammation, and promoting neuroregeneration." (PMID 41012526, 2025). "The decrease in RBC count and HGB may be directly related to the COVID-19 inflammatory process, due to the action of immune factors, mainly interferons and interleukins, which inhibit the production of erythropoietin (EPO)." (PMID 40362375, 2025). "Dysregulation of the erythropoietin pathway in severe COVID-19 in ESKD patients may also be relevant to immune function since erythropoietin is known to effect both innate and adaptive immunity." (PMID 36522333, 2022). "Nevertheless, employing EPO in severe COVID-19 for improving acute and downstream outcome (long COVID), requires watchful and comprehensive safety management as much as in all other EPO indications and, in particular, when using high doses of EPO to obtain sufficient levels also in brain." (PMID 34565332, 2021). "EPO resistance and deficiency are common in CKD patients, and supplementation with EPO might be a conjunctive strategy in managing the cytokine storm in CKD patients with COVID-19." (PMID 34452010, 2021). "These were the only COVID-19 cases who received EPO analogues we became aware of and had access to." (PMID 34565332, 2021). "EPO administration is indeed under investigation as a potential adjuvant treatment in COVID-19." (PMID 34573092, 2021).
COVID-19 (continued). "Surprisingly, recent reports showed decreased serum EPO levels in patients with severe COVID-19." (PMID 34565332, 2021). "Hence, at this point, we can only present as further supporting hints for our concept, 4 male patients with severe COVID-19 who were treated with EPO analogues." (PMID 34565332, 2021). "Taken together, EPO might have the potential to improve outcome of COVID-19 patients regarding acute as well as chronic-progressive downstream sequelae of the central and peripheral nervous system." (PMID 32546125, 2020). "This protective, balancing EPO mechanism might also be exploited for COVID-19 invasion into the brain, since in microglia, the NLRP3 inflammasome becomes (over) activated, too, when these cells sense virus." (PMID 32546125, 2020). "Erythropoietin (EPO) is the main signal driving erythropoiesis and often has been proposed as a possible adjuvant in therapies against COVID-19; among the genes screened, EPO showed down-regulation in agreement with the literature, possibly being a contributing cause to hypoxia in severe COVID-19." (PMID 38928376, 2024). "We identified gene signatures related to iron homeostasis, erythropoietin signaling, heme biosynthesis, and iron uptake that we grouped into processes contributing to erythropoiesis, as well as upregulation of erythrocyte function in fatal COVID-19 compared to COVID-19 survivors." (PMID 39161760, 2024). "Thus, EPO could be a potential bio-replenishment to reverse FeRD in COVID-19 and help reset HMRD in PASC patients." (PMID 38555403, 2024). "Due to the similarity of hypoxia-induced symptoms in COVID-19 and high-altitude disorders such as acute mountain sickness and high-altitude pulmonary edema, some initial studies had also suggested using drugs like nifedipine, phosphodiesterase inhibitors, erythropoietin, and dexamethasone." (PMID 36788813, 2023). "To elucidate whether the expression of DDC, ACE2, dACE2, or EPO are also altered in the nasopharyngeal tissue of COVID-19 patients with severe symptoms, we examined 21 samples obtained by SARS-CoV-2 infected patients admitted to the ICU and compared them to the Mild CoV-2 and Negative groups." (PMID 36611805, 2022). "After > 20 years of own experience in translational work on the brain EPO system, including many clinical trials, we feel that the following points need to be addressed in the context of this review and before presenting our design of a proof-of-concept trial on EPO treatment in COVID-19 below." (PMID 32546125, 2020). ",37, 38, 39 Accordingly, PTBP1 knockdown in primary CD34 cells treated with erythropoietin (EPO) resulted in the detection of OS/TS chimeras, which were also shown to have a significant correlation with asymptomatic disease status in COVID-19 patients." (PMID 40110491, 2025). "Innate Fe-Redox regulators such as lactoferrin (LF), heme oxygenase (HO)-1, erythropoietin (EPO), and hepcidin (HEP) serve as front-line innate barriers against free radical (ROS/RNS) damage and hyper-immune responses during COVID-19 and PASC27." (PMID 38555403, 2024). "Innate Fe-Redox regulators such as lactoferrin (LF), heme oxygenase-1 (HO-1), erythropoietin (EPO), and hepcidin (HEP) serve as first innate barriers against free radical damage and hyper-immune responses during COVID-19 and PASC27." (PMID 38555403, 2024). "Another review suggested that timely use of recombinant human erythropoietin (EPO), EPO analogs, acetylsalicylic acid, bioactive lipids, or FGF23 antagonists in genetically predisposed adults with the angiotensin-converting enzyme (ACE) D allele may induce detrimental effects in COVID-19 patients." (PMID 37637614, 2023). "Interestingly, erythropoietin could be a candidate for the supportive treatment of COVID-19." (PMID 34659373, 2021). "In addition, host proteases that are induced in severe COVID-19 might proteolyse EPO." (PMID 34565332, 2021).
COVID-19 (continued). "We recap here evidence that supports the use of human recombinant erythropoietin (EPO) for ameliorating course and outcome of seriously ill COVID-19 patients." (PMID 32546125, 2020). "Regarding hepcidin/iron and hepcidin/EPO ratios, they have not been explored in COVID-19 so far but in some other diseases." (PMID 38892911, 2024). "EPO treatment could restore Hb levels, increase red blood cell (RBC) count, and improve O2 delivery to the tissues, thereby help in the recovery of both COVID-19 and PASC patients." (PMID 38555403, 2024). "Because both LDH and FIB are hypoxia-regulated genes, we also investigated the expression of the hypoxia marker genes EPO, GLUT1, and HIF-1α in whole blood samples of the two COVID-19 patient cohorts (Ward/CoV-2 and ICU/CoV-2) and compared them to the healthy subjects." (PMID 36611805, 2022). "Since DDC and ACE2 expression is regulated by hypoxia and the HIF-target immune-modulatory gene EPO, we concurrently examined the expression profile of EPO in COVID-19 patients compared to the non-infected individuals." (PMID 34185793, 2021). "Tissue proteomic studies in turn showed the induction of hypoxia pathways in different organs of patients who deceased from COVID-19, but did not list EPO." (PMID 34565332, 2021). "Viral load and mRNA levels of DDC, ACE2, dACE2, ISG56 and EPO were quantified by RT-qPCR in nasopharyngeal swab samples from COVID-19 patients, showing no or mild symptoms, and from non-infected individuals." (PMID 34185793, 2021). "Therapeutic supplementation with EPO and vitamin D in different stages of CKD might be essential for maintaining the efficacy of the COVID-19 vaccine, although evidence for this is insufficient." (PMID 34452010, 2021). "All the examined pathological conditions induced hypoxia, with ARDS and COVID-19 depressing the hematopoietic response without remarkable effects on erythropoietin." (PMID 34573092, 2021).
renal fibrosis (38 papers, 2013 to 2026). A final common manifestation of a wide variety of chronic kidney diseases characterized by glomerulosclerosis and tubulointerstitial fibrosis. "The reduction or loss of the ability of activated fibroblasts to produce erythropoietin is a major cause of renal anemia in kidney injury, which exacerbates renal fibrosis." (PMID 35188068, 2022). "Myofibroblastic transformation of REPs, which causes REPs to lose their EPO-producing ability, is one of the major sources of myofibroblasts contributing to renal fibrosis." (PMID 33942716, 2021). "In renal fibrosis, the reduced or even loss of the ability of activated fibroblasts to produce erythropoietin is a major cause of renal anemia." (PMID 34560842, 2021). "In the previous study, we have demonstrated that proximal tubule injury alone can drive this phenotypic change and lead to renal fibrosis and deficiency in EPO production." (PMID 29259716, 2017). "Persistent inflammation and transition of pericytes to myofibroblasts cause renal fibrosis and diminishing of erythropoietin production." (PMID 24359941, 2013). "In CKD patients, however, sustained inflammation in renal fibrosis becomes the major contributor to EPO deficiency, as the damaged REPs in fibrotic kidneys transform into myofibroblasts, causing the concomitant repression of their ability to produce EPO." (PMID 37623232, 2023). "We showed that the combination of EPO and urinary albumin could predict major renal responses more accurately because the percentage of urinary albumin excretion reflected the cause of RI in MM and the level of EPO reflected renal fibrosis." (PMID 32311841, 2020). "Another proposed mechanism is the stimulation of erythropoietin production, facilitated by reduced renal fibrosis and improved survival of erythropoietin-producing cells." (PMID 41267697, 2025). "Consistently, our results indicate that Sult1a1-KO partly improved EPO production and progressive renal fibrosis was further suppressed by the administration of rhEPO to Sult1a1-KO mice." (PMID 37511089, 2023). "To confirm the impact of erythropoietin (EPO) on renal fibrosis, we evaluated the time-dependent expression of EPO." (PMID 37511089, 2023). "Sult1a1-KO mice exhibited reduced renal fibrosis, inflammation, and apoptosis and improved EPO production." (PMID 37511089, 2023). "Although the treatment of EPO against renal fibrosis is under investigation, a high dose of EPO was found to contribute to fibrogenesis in the long term." (PMID 37511089, 2023). "Elevated levels of pro-inflammatory cytokines and inflammation-related indicators characterise renal fibrosis in CKD and the loss of EPO production." (PMID 37623232, 2023). "Abnormal glomerular structure, renal fibrosis and matrix accumulation were observed in kidney tissues of mice in Model group compared with the mice of the control group, while EPO administration alleviated these histological changes." (PMID 35656290, 2022). "Inhibiting senescence by erythropoietin preserves tubular epithelial cell regeneration and ameliorates renal fibrosis in CKD." (PMID 36091755, 2022). "The inflammatory milieu in the kidney is one of the major contributors to renal fibrosis, which in turn facilitates REP conversion into myofibroblasts and the concomitant loss of EPO production capability." (PMID 33942716, 2021). "Neuroprotective agents, dexamethasone, and neurotrophins in agreement with the neural crest origin of REP cells restore EPO production and alleviate renal fibrosis." (PMID 34576149, 2021). "When fibroblasts convert to a myofibroblast phenotype in models of renal fibrosis, they lose the ability to produce EPO." (PMID 31943786, 2020). "The aims of this review were to briefly review the scientific evidence regarding the relationship of the therapeutic use of EPO with renal fibrosis." (PMID 32154256, 2020).
renal fibrosis (continued). "Lastly, we believe that the many developments and unremitting efforts from multiple medical disciplines will eventually establish a basis for the use of EPO as a treatment for renal fibrosis and will help guide future research in this area." (PMID 32154256, 2020). "Studies of the mechanism of renal fibrosis and of potential measures of prevention and treatment have focused on erythropoietin (EPO), a hormone best known as a regulator of red blood cell production." (PMID 32154256, 2020). "The aim of the present review is to briefly discuss the role of EPO in renal fibrosis, to identify its possible mechanisms in preventing renal fibrosis, and to provide novel ideas for the use of EPO in future treatments of renal fibrosis." (PMID 32154256, 2020). "It seems that renal fibrosis has special pathways, because mesangial cells, erythropoietin-producing cells, and tubular epithelial cells exist only in the kidney and are involved together in developing renal fibrosis." (PMID 31467925, 2019). "The in vitro findings clearly support that COLI accumulation that takes place in renal fibrosis induces FAK activation in EPO‐producing interstitial fibroblasts, which in its turn increases proteasome activity." (PMID 28857467, 2018). "More recent findings have revealed the cellular mechanism of kidney erythropoietin synthesis and the following events leading to renal fibrosis." (PMID 24359941, 2013). "Recent studies have unveiled the cellular mechanism of renal erythropoietin synthesis and the following events leading to renal fibrosis." (PMID 25340134, 2013). "The important role of erythropoietin (EPO) in the treatment of renal fibrosis induced by urinary tract obstruction has been documented in numerous studies; however, its underlying molecular mechanisms are not yet fully understood, particularly its role in regulating immunity and inflammation." (PMID 41847398, 2026). "Moreover, in a UUO of renal fibrosis in mice, erythropoietin (EPO) treatment was found to suppress the accumulation of myofibroblasts and the expression of α1(I) collagen mRNA, ultimately alleviating the progression of renal fibrosis." (PMID 40305351, 2025). "Therefore, curing renal fibrosis would improve renal anemia by protecting EPO-producing fibroblasts." (PMID 36725898, 2023). "Such high doses have been proven clinically unsafe and may increase cardiovascular complications, thus raising concerns regarding the clinical implementation of high-dose EPO to treat renal fibrosis." (PMID 32993806, 2020). "We therefore believe that EPO may also play a critical role in the development of renal fibrosis, but the mechanism of this effect requires further examination." (PMID 32154256, 2020). "These recent studies have found that EPO may also provide efficient protection against renal fibrosis." (PMID 32154256, 2020). "An animal study demonstrated that EPO ameliorates renal fibrosis and podocyte injury." (PMID 31619722, 2019). "Furthermore, activation of the erythropoietin (EPO) signaling pathway has been demonstrated to reduce oxidative stress and mitochondrial activity, thereby inhibiting the accumulation of bone marrow–derived fibrocytes and alleviating renal fibrosis." (PMID 41596210, 2026). "In Sult1a1-KO mice, EPO mRNA expression was improved considerably; UUO-induced renal fibrosis was further attenuated by recombinant human erythropoietin (rhEPO)." (PMID 37511089, 2023). "Hypoxia-inducible factor-prolyl hydroxylase (HIF-PHD) inhibitors are therapeutic agents for renal anemia that work through HIF2-mediated upregulation of erythropoietin (EPO) and have also been reported to suppress renal fibrosis." (PMID 36725898, 2023). "One study reported therapeutic effects on renal fibrosis and renal anemia after providing UCG, which was likely achieved by modulating transforming growth factor-β and erythropoietin signaling pathways in a mouse model." (PMID 36297351, 2022).